MYH9 (myosin heavy chain 9)
Diseases named in the same sentence as MYH9 in open-access papers (continued):
Sharing a sentence is not in itself a finding about the gene and the disease.
squamous cell carcinoma (17 papers, 2015 to 2025). A carcinoma arising from squamous epithelial cells. "In a 19-year-old female harboring a germline MYH9 variant, a right tongue ulcer was detected, and a biopsy confirmed the presence of squamous cell carcinoma." (PMID 39149512, 2024). "In squamous cell carcinoma, a reduced expression level of MYH9 (the heavy chain of NM2A) was associated with a higher invasion rate and distant metastases." (PMID 35205819, 2022). "Repression of MYH9 predisposed mice to squamous cell carcinoma (SCC), as MYH9 was identified from an RNA interference screen." (PMID 37200287, 2023). "For example, MYH9, the heavy chain of myosin II, acts as a tumor suppressor in squamous cell carcinomas of the head and neck, while it promotes invasive behavior in breast tumor cells." (PMID 28388691, 2017). "In further analyses, MYH9 expression was significantly correlated with poorer survival in patients with either adenocarcinoma (P = 0.007) or squamous cell carcinoma (P = 0.032)." (PMID 25826333, 2015). "MYH9 expression was more frequently detected in adenocarcinoma than in squamous cell carcinoma and other histological subtypes (P = 0.014)." (PMID 25826333, 2015). "Of the 266 surgically resected NSCLCs, including 203 adenocarcinomas, 51 squamous cell carcinomas, 10 large cell carcinomas, and 2 adenosquamous cell carcinomas, positive MYH9 expression in tumor cells was observed in 102 cases (38.3%)." (PMID 25826333, 2015). "The present study examined MYH9 expression in resected NSCLCs including squamous cell carcinomas of pathological stage I-III, and analyzed the correlation with clinicopathological parameters of patients and its prognostic significance." (PMID 25826333, 2015). "Myh9, which encodes nonmuscle myosin IIa, has been identified as tumor suppressor of squamous cell carcinomas (SCCs)." (PMID 29484121, 2018). "Therefore, high MYH9 expression may be one of the most important markers in prognosis of squamous cell carcinoma." (PMID 32788880, 2020). "The 5-year survival probability was 69 and 85% for MYH9-positive and -negative adenocarcinoma patients, respectively, and 43 and 74% for MYH9-positive and -negative squamous cell carcinoma patients, respectively." (PMID 25826333, 2015).
focal segmental glomerulosclerosis (15 papers, 2010 to 2025). A renal disorder characterized by sclerotic lesions in the glomeruli. "Familial segregation of microhematuria and proteinuria can result from defects in one of the COL4A3/A4/A5 genes or in genes causing hereditary focal and segmental glomerulosclerosis or MYH9-related disorders." (PMID 36553470, 2022). "Recently, increased proteinuria, podocyte injury, and focal segmental glomerulosclerosis have been observed in a mouse model harboring MYH9 E1841K mutation in response to a high-salt diet." (PMID 33001861, 2020). "One reason cited is a genetic variation in the MYH9 region on chromosome 22, with focal segmental glomerulosclerosis found in 74% of African American adults compared to 4% of White adults." (PMID 40364877, 2025). "We summarized the clinical phenotype and reported a novel variant in MYH9 in a child with focal segmental glomerulosclerosis (FSGS) and reviewed the relevant literature to better understand MYH9-RD." (PMID 40416435, 2025). "Single nucleotide polymorphisms (SNPs) in MYH9 were found to predict susceptibility to HIV-associated nephropathy (HIVAN), focal segmental glomerulosclerosis (FSGS) and endstage renal disease." (PMID 24949636, 2014). "Similar association was found in variants spanning exon 14–23 of the MYH9 gene in 852 focal segmental glomerulosclerosis (FSGS) and 433 non-diabetic ESRD patients, but not for 476 diabetic-ESRD patients when compared to 222 controls." (PMID 30359254, 2018). "In 2008, the gene, MYH9, was found to explain both the higher rates of focal segmental glomerulosclerosis (FSGS), a steroid-resistant form of nephrotic syndrome, and the higher rates of ESRD among African Americans compared to European Americans." (PMID 23351121, 2013). "According to genome-wide association studies (GWAS), polymorphisms in MYH9 have been reported to be strongly associated with ESRD, including focal segmental glomerulosclerosis (FSGS), global glomerulosclerosis, diabetic nephropathy, and collapsing glomerulopathy." (PMID 37833721, 2023). "Polymorphisms in Myosin Heavy Chain 9 (MYH9) have also been shown to be associated with CKD risk in admixed non-diabetic nephropathy, and focal segmental glomerulosclerosis (FSGS)." (PMID 29665793, 2018).
glioma (15 papers, 2008 to 2025). A benign or malignant brain and spinal cord tumor that arises from glial cells (astrocytes, oligodendrocytes, ependymal cells). "A recent study observed increased MYH9 expression in gliomas, and this elevated expression was associated with WHO grading." (PMID 39149512, 2024). "MYH9 knockdown experiments confirmed the association between MYH9 and glioma progression." (PMID 34635636, 2021). "Overexpression of WD repeat domain 1 promotes the proliferation of patient-derived glioma cells, indicating a synergistic effect with MYH9." (PMID 39988672, 2025). "To investigate the biological functions of MYH9 in glioblastoma, we first discovered through a glioma chip (HBraG160Su01) that the expression of MYH9 increases with the pathological grade." (PMID 39988672, 2025). "Like in glioma cells, MYH9 promotes GSK3β protein degradation via ubiquitination to promote the nuclear translocation of β-catenin." (PMID 39273383, 2024). "Treatment with apatinib indirectly decreased the levels of MYH9 to inhibit the invasion and migration of glioma cells." (PMID 39273383, 2024). "Apatinib targets platelet-responsive protein 1 (THBS1) in glioma cells, thereby inhibiting glioma cell malignancy through its interaction with MYH9." (PMID 39149512, 2024). "For example, MYH9 is involved in glioma proliferation and drug resistance through the regulation of NAP1L1 deubiquitination." (PMID 39550407, 2024). "Elevated MYH9 expression can drive the acquisition of a malignant phenotype in glioma cells and contribute to their resistance to chemotherapy." (PMID 39149512, 2024). "The western blotting (WB) results showed higher MYH9 expression levels in three fresh glioma tissues than in three adjacent normal tissues." (PMID 37770914, 2023). "We used immunohistochemistry to assess MYH9 expression in 168 glioma tissues compared with 15 paratumoral tissues." (PMID 37770914, 2023). "The results of this assay demonstrated that MYH9 greatly decreased the ubiquitination level of NAP1L1 in glioma cells." (PMID 37770914, 2023). "The BIOGRID database, combined with Co-IP, was used to explore the molecular mechanisms through which MYH9 regulates the c-Myc pathway in glioma." (PMID 37770914, 2023). "Our results showed that MYH9 increased the proliferation and temozolomide resistance of glioma cells." (PMID 37770914, 2023). "The CCK8 assay results showed that NAP1L1 overexpression enhanced cell proliferation in MYH9-silenced glioma cells." (PMID 37770914, 2023). "In summary, these findings showed that MYH9 expression in glioma tissues was higher than that in adjacent tissues and that MYH9 acts as an oncogene that can predict poor prognosis in patients with glioma." (PMID 37770914, 2023). "To verify the functions of MYH9 in glioma cells, we first determined the mRNA levels of MYH9 expression using RT‒qPCR in 15 glioma tissues and 15 paratumoral tissues." (PMID 37770914, 2023). "Altogether, our results show that MYH9 plays a role in glioma progression by regulating NAP1L1 deubiquitination." (PMID 37770914, 2023). "The univariate and multivariate Cox regression analysis results also suggested that MYH9 expression was negatively correlated with the overall survival of glioma patients." (PMID 37770914, 2023). "The expression of MYH9 was positively correlated with the Ki-67 index, recurrence, and WHO grade, indicating that MYH9 contributes to the progression of glioma." (PMID 37770914, 2023). "The expression of MYH9 in glioma tissue was also found to be significantly correlated with the pathological grade of the tumor (WHO II vs. WHO III vs. WHO IV)." (PMID 37770914, 2023). "The BIOGRID database combined with co-IP analysis was used to investigate the molecular mechanisms by which MYH9 promotes the c-Myc pathway in glioma." (PMID 37770914, 2023). "The findings of the present research suggest that MYH9 is involved in the pathogenesis of glioma and is a potential target for its clinical treatment." (PMID 37770914, 2023).
glioma (continued). "Using immunohistochemistry (IHC) scores, the MYH9 expression levels in 168 glioma samples were determined." (PMID 37770914, 2023). "In the present study, using the CPTAC and TCGA datasets, we demonstrated that MYH9 is overexpressed in glioma cells." (PMID 37770914, 2023). "The results showed that the MYH9 mRNA expression level was higher in glioma tissues than in paratumoural tissues." (PMID 37770914, 2023). "Using the CPTAC portal, we found that the protein expression of MYH9 was upregulated in glioma patients." (PMID 37770914, 2023). "We found that MYH9 mRNA expression was significantly upregulated in patients with glioma in the TCGA/GTEx dataset." (PMID 37770914, 2023). "Next, we found that the knockdown of MYH9 reduced glioma cell proliferation and temozolomide resistance in vitro." (PMID 37770914, 2023). "An endogenous co-IP assay was performed to indicate that MYH9 interacted with NAP1L1 in glioma cells." (PMID 37770914, 2023). "Overall, these findings suggest that MYH9 has prognostic and therapeutic value for the evaluation and clinical treatment of glioma." (PMID 37770914, 2023). "The results of the OS and DFS analyses indicated that the upregulation of MYH9 was negatively correlated with the overall survival of patients with glioma." (PMID 37770914, 2023). "Our study demonstrated that both HMGA1 and MYH9 promote glioma cell proliferation, invasion, migration, and TMZ resistance." (PMID 34887392, 2021). "Subsequently, the data for HMGA1 and MYH9 mRNA expression in gliomas were extracted from the Chinese Glioma Genome Atlas (CCGA) database." (PMID 34887392, 2021). "To validate these findings, we silenced c-Jun expression in glioma cells; and qPCR and western blotting revealed that knockdown of c-Jun markedly reduced MYH9 expression." (PMID 34887392, 2021). "But another study reported that overexpression of MYH9 abrogated the migration-inhibiting effects of the endogenous aryl hydrocarbon receptor agonist, indicating that MYH9 is essential for glioma cell migration." (PMID 34887392, 2021). "For gliomas, overexpression of MYH9 contributes to cell migration ability, suggesting major roles in cell migration and tumor invasion." (PMID 34887392, 2021). "Strong MYH9 staining was primarily observed in the cytoplasm and secondarily in the nucleus in glioma tissues, whereas low expression was observed in NB tissues." (PMID 34887392, 2021). "Myosin heavy chain 9 (MYH9) plays an essential role in human diseases, including multiple cancers; however, little is known about its role in gliomas." (PMID 34887392, 2021). "The potential involvement of the THBS1/MYH9 axis on apatinib-mediated inhibition of glioma cell migration and invasion was demonstrated in previous reports." (PMID 34635636, 2021). "Our data tend to provide new insights into the molecular function of HMGA1 and MYH9 as well as its regulatory mechanisms in gliomas." (PMID 34887392, 2021). "In this study, we found that MYH9 was overexpressed in glioma samples, which promoted glioma cell proliferation, invasion, migration, and TMZ resistance." (PMID 34887392, 2021). "In this study, immunoprecipitation led to the discovery of MYH9 as a likely binding partner of THBS1 in glioma cells." (PMID 34635636, 2021). "MTT and Edu incorporation assays showed that MYH9 upregulation reversed the shHMGA1-mediated reduction of proliferation in glioma cells." (PMID 34887392, 2021). "Using Kaplan–Meier analysis and the log-rank test, HMGA1 expression, MYH9 expression, age, pathological diagnosis, and WHO grade were found to be significantly associated with the overall survival of glioma patients in univariate analysis (both P < 0.05)." (PMID 34887392, 2021). "IHC revealed that the protein expression of HMGA1 and MYH9 also was increased in glioma tissues compared with NB." (PMID 34887392, 2021).
glioma (continued). "Additionally, a 2023 study reported that gambogic amide forms a complex with WD repeat domain 1, Cofilin, and MYH9, inhibiting the invasion of patient-derived glioma cells by disrupting the cytoskeleton." (PMID 39988672, 2025). "Glioma cells overexpress MYH9 and high mobility group A1 (HMGA1, a chromatin structural protein)." (PMID 39273383, 2024). "THBS1 interacts with MYH9 to increase the malignancy of glioma cells." (PMID 39273383, 2024). "Through direct interaction with WDR1, GA-amide promoted the formation of a complex involving WDR1, MYH9 and Cofilin, which accelerate the depolymerization of F-actin to inhibit the invasion of patient-derived glioma cells (PDCs) and induce PDC apoptosis via the mitochondrial apoptotic pathway." (PMID 37935665, 2023). "Nevertheless, the function of MYH9 in glioma has remained unclear." (PMID 37770914, 2023). "Additionally, the upregulated expression of MYH9 was found to be correlated with a poor prognosis for patients with glioma." (PMID 37770914, 2023). "To explore in more detail whether NAP1L1 participates in the promotion of MYH9 in glioma, we transfected MYH9-silenced glioma cells with an NAP1L1 plasmid." (PMID 37770914, 2023). "In addition, NAP1L1 was found to affect MYH9-mediated regulation of the c-Myc pathway in glioma cells." (PMID 37770914, 2023). "The role of MYH9 in glioma should be explored further in future research." (PMID 37770914, 2023). "Since proteins can be degraded via the ubiquitin‒proteasome pathway, we attempted to determine whether MYH9 regulates NAP1L1 degradation by inhibiting its ubiquitination in glioma cells." (PMID 37770914, 2023). "The present research aimed to investigate the role of MYH9 in glioma and determine whether MYH9 is involved in the temozolomide chemoresistance of glioma cells." (PMID 37770914, 2023). "To further clarify the role of MYH9 and NAP1L1 in glioma, we attempted to determine whether MYH9 participates in regulating the expression of NAP1L1." (PMID 37770914, 2023). "In the present research, the molecular function of MYH9 in glioma cells was investigated." (PMID 37770914, 2023). "Next, we assessed the relationship between glioma patient prognosis and MYH9 expression." (PMID 37770914, 2023). "Interestingly, WB showed that the expression of γ-H2AX, a biomarker for DNA double-strand breaks, was upregulated in glioma cells with MYH9 knockdown." (PMID 37770914, 2023). "The endogenous Co-IP assay showed that MYH9 interacted with NAP1L1 in glioma cells." (PMID 37770914, 2023). "Thus, targeting MYH9 is a potential therapeutic strategy for the clinical treatment of glioma in the future." (PMID 37770914, 2023). "Higher expression levels of MYH9 indicated shorter survival times in patients with glioma." (PMID 37770914, 2023). "In addition, the EdU assay and clone formation assay confirmed that downregulation of MYH9 decreased the viability of glioma cells." (PMID 37770914, 2023). "Together, these findings suggest that MYH9 affects glioma progression by interacting with NAP1L1." (PMID 37770914, 2023). "In glioma and pancreatic cancer, MYH9 may interact with GSK3β, subsequently triggering the Wnt/β-catenin signaling pathway to facilitate cancer progression." (PMID 36139430, 2022). "Co-IP and mass spectrometry analysis revealed that THBS1 could interact with myosin heavy chain 9 (MYH9) in glioma cells." (PMID 34635636, 2021). "In recent years, studies have found that MYH9, as a protein involved in cytoskeletal reorganization, pseudopodia formation, and migration, plays an important role in the progression of glioma and other solid tumors, and MYH9 acts as an oncogene in almost all solid and hematological tumors." (PMID 34635636, 2021). "We used the MYH9-overexpression vector (MYH9 OE) to identify the phenotype of U87 and LN229 cells after functional recovery of MYH9, and the results also suggested that MYH9 promoted proliferation, invasion, migration, and chemotherapy resistance in glioma cells." (PMID 34887392, 2021).